MYC (MYC proto-oncogene, bHLH transcription factor)
Diseases named in the same sentence as MYC in open-access papers (continued):
Sharing a sentence is not in itself a finding about the gene and the disease.
breast cancer (continued). "NDRG1 is located on chromosome 8q24.3, near MYC, and amplification of this region is both common and prognostic in breast cancer." (PMID 38611020, 2024). "c-MYC is also responsible for the crosstalk between breast cancer cells and the tumour microenvironment by regulating proteins in cancer cells as well as immune infiltration." (PMID 38662248, 2024). "In breast cancers, MYC overexpression has been reported at transcriptional, post transcriptional and translational level." (PMID 38965558, 2024). "To further explore the potential of palbociclib to induce a response in patients, we conducted a pharmacological test of palbociclib effectiveness on mini-PDX models derived from breast cancer tissues in which MYC was expressed at different levels." (PMID 38424044, 2024). "Early studies in breast cancer showed that BRD4 functions as a tumour suppressor and its overexpression in a MYC-driven murine mammary tumour cell line reduces breast cancer growth in vivo." (PMID 38191874, 2024). "Previous studies have reported that DNA methylation epigenetically silences the MYC gene in canine mammary tumors and the NKX3.1 gene in prostate cancer." (PMID 39185058, 2024). "Considering that upregulation of MYC is one of the well-known mechanisms by which ER+ breast cancers acquire endocrine therapy resistance, our study points to a possible role for G-proteins in mediating endocrine therapy response." (PMID 38965558, 2024). "Sanger sequencing identified the poly U mRNA-stabilizing elements on the 3′UTR of the c-MYC gene that were 99% conserved across breast cancer cell lines." (PMID 39123391, 2024). "MYC is involved in tumor progression and in the response to therapy of both melanoma and breast carcinoma." (PMID 38755629, 2024). "MYC is a proto-oncogene in many cancers, including Burkitt's lymphomas, lung carcinoma, breast carcinoma, and colon carcinoma." (PMID 38462658, 2024). "Of the 294 oncogenic TFs, the androgen and estrogen receptors, the BRCA1 and BRCA2 genes, MYC and GATA3 stand out for their association with breast cancer subtypes." (PMID 37564937, 2023). "For some known genes related to breast cancer (e.g., MYC, IGFBP5, CCND1, ESR1), we confirmed epithelial cells showed higher expression levels." (PMID 37340002, 2023). "It will be interesting to retrospectively evaluate MYC status using clinicogenomic data from the BOLERO-2 trial or other clinical trials that evaluated everolimus-based therapies for ER+/HER2− breast cancer in different first-line settings." (PMID 37642941, 2023). "Here, we abrogated AP4 expression in the breast cancer cell line MCF-7 harboring an ectopic, inducible c-MYC allele previously generated by us using a CRISPR/Cas9 approach." (PMID 36831504, 2023). "Treatment of breast cancer cells with luteolin inhibited the NF-κB pathway and subsequent c-MYC expression, which significantly reduced hTERT expression levels." (PMID 37612721, 2023). "The data, therefore, suggests an essential role for c-MYC as a mediator of the biological effects of miR-616 in breast cancer cells." (PMID 37685841, 2023). "LINC00839 promotes chemotherapy resistance in breast cancer by targeting MYC to activate the PI3K/AKT signaling pathway." (PMID 36426411, 2023). "In vitro and in vivo induction of MYC conferred mTORi resistance in mouse and human breast cancer models." (PMID 37642941, 2023). "HN1 expression has been associated with MYC, where HN1 overexpression was linked with increased migration and invasiveness in Breast cancer." (PMID 36829467, 2023).
breast cancer (continued). "By detecting the expression of related genes and proteins, the mechanism of the promising candidate increasing intracellular ROS and inducing apoptosis of breast cancer cells through the c-MYC/SOD2 pathway was clarified." (PMID 38275631, 2023). "They identified different proteins required for the survival of MYC-driven breast cancer cells, where TNBC is an example." (PMID 37686639, 2023). "CAFs produce fibroblast growth factor 2 (FGF2), followed up with activation and recruition of ERα and PRBΔ4 to the MYC regulatory sequence leading to the breast cancer growth." (PMID 36721232, 2023). "FGF2 induces breast cancer growth by activating and recruiting ERα and PRBΔ4 isoforms to MYC regulatory sequences." (PMID 37445737, 2023). "MYC amplification is often enriched in high-grade breast cancers, triple-negative breast cancers, and basal-like breast cancers." (PMID 37805590, 2023). "HRAS exon 5 inclusion was found to be anticorrelated with MYC activity across prostate and breast cancers." (PMID 37399401, 2023). "For example, in several reported cases of metastatic breast cancer, MYC duplications in primary tumors were found to expand to higher-copy MYC amplification in the metastatic more aggressive breast cancers." (PMID 36504387, 2023). "Combined with above, CAFs have a dual function on breast cancer tumor growth and c-MYC is a critical mediator during the process." (PMID 36721232, 2023). "In breast cancer patients, c-MYC has been confirmed to be highly expressed and lead to the occurrence and development of breast cancer." (PMID 36721232, 2023). "The gene expression characteristics of this breast cancer subtype include keratin 5, keratin 17, intergrin-B4, laminin, and a high expression of proliferation-related genes such as amplification of MYC, CDK6, CCNE1." (PMID 37047814, 2023). "Treatment of ZINC15675948 (IC50) significantly downregulated c-MYC (p ≤ 0.05) in both leukemia and breast cancer cell lines, indicating that ZINC15675948 inhibited c-MYC at the gene expression level." (PMID 37570631, 2023). "Specifically, IGF2BP1 maintains the stability of MYC by binding to the coding region determinant of m6A-modified MYC in a hypoxic microenvironment, thereby promoting the self-renewal of breast cancer stem cells." (PMID 37554271, 2023). "Orthotopic modeling of mouse ILC tumors and human breast cancer–derived xenografts confirmed that MYC is an in vivo and clinically relevant driver of mTORi resistance." (PMID 37642941, 2023). "By modulating SRC-1 expression, c-MYC activates colony-stimulating factor 1 (CSF-1) and enriches macrophages to enhance breast cancer metastasis." (PMID 36721232, 2023). "In summary, c-MYC promotes the tumor progression of breast cancer by inhibiting the activation of immune cells in the TME." (PMID 36721232, 2023). "This compound was also shown to repress c-MYC expression in MCF-7 breast cancer cells at 4 and 10 μM concentrations." (PMID 36979947, 2023). "miR-155 can also promote glycolysis in breast cancer through the PIK3R1-FOXO3A-cMYC pathway, miRNA-155 can antagonize FOXO3A, which can destroy the stability of c-MYC." (PMID 37204526, 2023). "Second, we orthotopically transplanted human MDA-MB-468 breast cancer cells expressing either Akaluc or MYC-P2A-Akaluc into the mammary glands of immunocompromised NOD-Prkdcscid-IL2rgTm1/Rj (NXG) female mice via intraductal injection." (PMID 37642941, 2023).
breast cancer (continued). "As a common driver of breast cancer, MYC amplification plays a role in emerging or acquired chemotherapy resistance during neoadjuvant treatment of TNBC." (PMID 37929934, 2023). "Aside in hematological malignancies, there have been reports on over expression of c-MYC in breast cancer 25,26." (PMID 38223598, 2023). "Another typical event in ASs is MYC amplification, especially in secondary angiosarcomas following breast cancer." (PMID 38137511, 2023). "For example, our study has reported that lactate dehydrogenase A (LDHA)-catalyzed lactate induces tumor acidic microenvironment to strengthen the binding capacity between USP28 and MYC, leading to MYC-driven breast cancer stem-like traits." (PMID 37845207, 2023). "Recently, it was demonstrated that the amplification of HER2 and deregulation of MYC accelerated tumorigenesis, metastasis, and lethality in breast cancer." (PMID 37801436, 2023). "The high mutational frequency of AURKA in the studied cohort of patients was very interesting, as this plays a role in promoting MYC expression in breast cancer stem cells." (PMID 37298642, 2023). "In breast cancer cells, Sapi and colleagues demonstrated that cytokine CSF-1 induces expression of c-MYC, enhancing tumorigenicity as well as invasive potential." (PMID 36721232, 2023). "Recently, the c-MYC-dependent control of FOSL1 in breast cancer has been further characterized by studying the NRG-dependent control of c-MYC stability." (PMID 37176013, 2023). "In this study, we demonstrated MYC activation to be a central mechanism of mTORi resistance in breast cancer." (PMID 37642941, 2023). "HER2-zero breast cancer was found to have gains in 08q24.21 (MYC) and 08p11.23 (FGFR1, ADGRA2, ZNF703)." (PMID 37264417, 2023). "A heat map generated using data from TCGA (BRCA- breast cancers) showed that OCT4 and MYC were overexpressed in basal-like breast cancers while SOX2 and KLF4 were down regulated in this subtype." (PMID 37515162, 2023). "When breast cancer cells express high octamer-binding transcription factor 4 (Oct4), they also show inhibition to breast cancer cells with low Oct4 expression, similar to c-MYC." (PMID 36624542, 2023). "Taken together, our results showed that MYC drives mTORi resistance in cell culture models of mouse and human breast cancer." (PMID 37642941, 2023). "Herein, we report that MAF1 is amplified in 39% of all breast cancer sub-types, and the observed amplification co-occurs with MYC." (PMID 37801436, 2023). "The basal-like breast cancers in cluster 5, however, displayed a very different gene expression pattern and were enriched with MYC-regulated genes (“MYC targets V1” and “-V2”), E2F-target genes, and genes associated with oxidative phosphorylation." (PMID 38111531, 2023). "MYC contributes to the generation of more competitive phenotypes; higher c-MYC breast cancer cells have higher numbers when cocultured with lower c-MYC breast cancer cells." (PMID 36624542, 2023). "Collectively, our data demonstrated that MYC drives resistance to clinically approved mTOR-targeted therapies in mouse models of murine and human breast cancer." (PMID 37642941, 2023). "In mouse models, several groups have demonstrated that overexpression of MYC alone is sufficient for the development of spontaneous mammary tumors with high penetrance." (PMID 37805590, 2023). "The typical examples are RAS-driven colorectal cancer and MYC-driven breast cancer, where with insufficient or impaired SUMOylation, cancer cells exhibit specific vulnerabilities differentiating from healthy cells." (PMID 37686409, 2023).
breast cancer (continued). "The co-expression network in TCGA breast cancer cohorts was significantly positively enriched in E2F targets pathway, G2M checkpoint pathway, mitotic spindle pathway, DNA repair pathway, MYC target pathway, MTORC1 signaling pathway, and glycolysis pathway." (PMID 36968583, 2023). "Compound 44 also showed the ability to inhibit c-MYC transcription in a concentration-dependent manner and had weaker effects in other oncogenes’ transcriptions, which shows the preference to silence the c-MYC gene in the breast cancer 4T1 cell line." (PMID 36979947, 2023). "The aim of this study was to investigate a natural product derivate of 1,2,4-oxadiazole, ZINC15675948, as a potential c-MYC inhibitor and its modes of action in leukemia and breast cancer cells." (PMID 37570631, 2023). "Here, we aimed to summarize and review the relevant research, thus to clarify c-MYC is a key mediator between breast cancer cells and TME." (PMID 36721232, 2023). "MYC and KLF4 expression showed the most highly correlated expression profile (r = 0.35, p < 0.05) in the pan-cancer analysis while OCT4 and MYC expression was most positively correlated in the breast cancer analysis (r = 0.29, p < 0.05)." (PMID 37515162, 2023). "The elevated c-MYC expression also mediates EMT in breast cancers, thus possibly explaining the partial-EMT observed in Api5 OE cells." (PMID 37095445, 2023). "Subsequently, another study conducted in a doxycycline-inducible MYC-driven murine breast cancer model found a correlation between the generation of lactate from HP [1-13C] pyruvate and the development or regression of MYC-driven tumors." (PMID 37233647, 2023). "SCRIB is located at locus 8q24.3, close to oncogene MYC, and is amplified in 10.3% of TCGA breast cancer cases." (PMID 36675340, 2023). "Ali and colleagues demonstrated that FTH1 silencing promoted cell growth in breast cancer leading to an increased c-MYC expression and reduced cell sensitivity to chemotherapy." (PMID 38001941, 2023). "In order to study the role of AP4 downstream of c-MYC in breast cancer cells, AP4 was inactivated in MCF-7/pRTR-c-MYC cells using a CRISPR/Cas9 approach." (PMID 36831504, 2023). "Several studies have reported the upregulation of c-MYC in different cancer cells and tumors, such as neuroblastomas, lung, and breast cancer." (PMID 37685841, 2023). "We queried ROC Plotter for breast cancer patients for transcriptomic-level MYC expression in response to anti-HER2 therapies." (PMID 37801436, 2023). "In HER2-positive breast cancer patients, the co-expression of c-MYC and PVT1 has been shown to play an important role in promoting tumor malignancy." (PMID 36624401, 2023). "The height of this amplicon in our studies includes aCGH log2ratios > 4 corresponding to FISH copy numbers > 20 consistent with amplification of genomic “drivers” such as HER2 and MYC in breast cancer and other solid tumors." (PMID 36635351, 2023). "Several transcriptional activators have been identified to regulate hTERT expression in breast cancer cells, including c-MYC, STAT3, NF-κB, ETS2, ERα, Sp1, KLF4, and ZEB1/YAP, among others." (PMID 37612721, 2023). "Breast cancer cells with high c-MYC expression are more prevalent, promoting tumor progression through macrophages." (PMID 36721232, 2023). "We report that MAF1 is amplified in 39% of all breast cancer sub-types, and the observed amplification co-occurs with MYC." (PMID 37801436, 2023). "Starved fibroblast supernatants reduced MYC expression levels in breast cancer cells and induced cancer stem cells death." (PMID 36721232, 2023).
breast cancer (continued). "Further investigations are needed to analyze the target MYC expression levels in each breast cancer subtype." (PMID 37759508, 2023). "We examined HER2, MAF1, and MYC expression in the five-year relapse-free breast cancer patient dataset, restricting our query to HER2-positive samples (n = 564)." (PMID 37801436, 2023). "In breast cancer, c-MYC is expressed at elevated levels in 30–50% and amplified in nearly 15% of cases." (PMID 36831504, 2023). "Taken together, multiple cytokines can promote breast cancer progression by upregulating c-MYC expression in cancer cells." (PMID 36721232, 2023). "MYC is a master transcriptional regulator that is amplified in approximately 15–20% of breast cancers and overexpressed in up to 35% of breast cancers." (PMID 37805590, 2023). "Perhaps most strikingly, the partial-EMT gene cluster is enriched for MYC target genes, and in line with this, MYC expression in basal-like breast cancers with partial-EMT features is higher than in basal-like cancers with post-EMT features." (PMID 38111531, 2023). "The MYC oncogene is a central driver in multiple cancers, such as breast cancer, liver cancer, colorectal carcinoma, prostatic neoplasia, ovarian cancer and lung cancer." (PMID 37755397, 2023). "MYC acts as a negative regulator of lncRNA to inhibit transcription of FGF13-AS1, forming an FGF13-AS1/IGF2BPs/MYC feedback pathway to inhibit breast cancer development and glycolysis." (PMID 37204526, 2023). "Estrogen enhances formation of MED1 condensates at the MYC oncogene in ER+ breast cancer cells and tamoxifen disrupts the formation of condensates." (PMID 35740532, 2022). "Etomoxir blocks tumor growth and metastatic features of breast cancer patient-derived xenografts (PDXs), in MYC-driven transgenic TNBC mouse models, and in MYC-overexpressing PDXs." (PMID 35831624, 2022). "MDA-MB-231 was chosen because it represents basal-like, triple-negative breast cancer, which is a subgroup of breast cancer with frequent MYC amplification and/or high MYC pathway activity." (PMID 36874405, 2022). "On the other hand, the dysregulation of MYC facilitates angiogenesis and metastasis, leading to poor prognosis in breast cancer patients." (PMID 36685821, 2022). "SF3A3 selectively regulates MYC-driven splicing and metabolic reprogramming, which, in turn, induce tumorigenesis and breast cancer plasticity." (PMID 35248043, 2022). "Collectively, these results support a direct transcriptional role for MYC in suppressing the expression of ZNF148 in breast cancer through chromatin occupancy." (PMID 36207293, 2022). "We have previously shown that expression of AP4 is directly induced by c-MYC in breast cancer cells, human diploid fibroblasts and SW620 CRC cells." (PMID 35624466, 2022). "On the contrary, the hMSCs derived from both sources enhanced breast cancer cell migration, possibly by increasing the expression of MYC, SNAI1, and TWIST genes in those cells." (PMID 36406002, 2022). "Even distant lethal breast cancer metastases from MYC-unamplified primary tumors often acquire MYC amplification." (PMID 36860495, 2022). "A clinical trial (Phase I/II; NCT04808362) started since 2021 has made Omomyc the first c-MYC inhibitor to reach clinical study in patients with advanced solid tumors, including breast cancer." (PMID 35267559, 2022). "Since MYC expression is strongly induced by ER activation 17,18, our results suggest that SCRIB is regulated by the ER-MYC pathway in ER+ breast cancer cells." (PMID 35501367, 2022).